NCR3 (natural cytotoxicity triggering receptor 3)
Description:
Cell membrane receptor of natural killer/NK cells that is activated by binding of extracellular ligands including BAG6 and NCR3LG1. Stimulates NK cells cytotoxicity toward neighboring cells producing these ligands. It controls, for instance, NK cells cytotoxicity against tumor cells. Engagement of NCR3 by BAG6 also promotes myeloid dendritic cells (DC) maturation, both through killing DCs that did not acquire a mature phenotype, and inducing the release by NK cells of TNFA and IFNG which promote DC maturation.
Synonyms: NKp30; CD337; 1C7; LY117; MALS
Tractability: Antibody: UniProt places it where antibodies can reach, with high confidence; its Gene Ontology location is reachable by antibodies, with high confidence; UniProt predicts a signal peptide or a membrane-spanning region.
Gene: Protein-coding gene on chromosome 6 (31,588,895 to 31,593,217, reverse strand). Ensembl gene ENSG00000204475.
Subcellular location: Cell membrane
Pathways (Reactome):
Immune System: Immunoregulatory interactions between a Lymphoid and a non-Lymphoid cell
Gene Ontology:
Molecular function: identical protein binding; immune receptor activity; protein binding
Biological process: immune response-activating cell surface receptor signaling pathway; natural killer cell activation; NK T cell activation; positive regulation of natural killer cell mediated cytotoxicity; cell recognition; immune response; inflammatory response
Cellular component: plasma membrane
Genetic constraint (gnomAD): Loss-of-function variants: 13 observed, 17.11 expected, observed/expected ratio (o/e) 0.76, 90% interval 0.49 to 1.21. The upper end of that interval is the gene's LOEUF score, 1.21, which puts it in group 5 of 6, group 1 being the genes least tolerant of losing a copy. Missense variants: 202 observed, 269.88 expected, observed/expected ratio (o/e) 0.75, 90% interval 0.67 to 0.84. Synonymous variants: 98 observed, 112.77 expected, observed/expected ratio (o/e) 0.87, 90% interval 0.74 to 1.03.
Homologues: Orthologues: macaque NCR3 (90% identical), chimpanzee NCR3 (83% identical), rat Ncr3 (55% identical), dog NCR3 (53% identical), zebrafish si:ch73-22o12.1 (17% identical), zebrafish zgc:113337 (16% identical), zebrafish pvrl2l (15% identical), zebrafish si:ch211-222f23.6 (14% identical), Drosophila melanogaster Fas3 (13% identical), zebrafish sc:d189 (13% identical), zebrafish si:ch211-141e20.2 (13% identical), zebrafish zgc:172122 (13% identical), and 1 more. Paralogues in human: NECTIN3 (20% identical), NECTIN2 (19% identical), NECTIN1 (19% identical), PVR (18% identical), NECTIN4 (18% identical), CADM2 (16% identical), CADM1 (15% identical), CADM3 (15% identical), CRTAM (14% identical), CADM4 (14% identical), CD226 (13% identical), CD200 (12% identical), and 2 more.
Diseases named in the same sentence as NCR3 in open-access papers:
NCR3 is named in the same sentence as 125 diseases in open-access papers, as found by Europe PMC text mining. Sharing a sentence is not in itself a finding about the gene and the disease. The quoted sentences say what the papers report.
melanoma (30 papers, 2009 to 2025). A malignant, usually aggressive tumor composed of atypical, neoplastic melanocytes. "Our data revealed heightened expression of CD8+ T cell markers (CD8a and CD8b) and NK cell markers (NCR1 and NCR3) in melanoma patients with elevated levels of cGAS/CCL5/CXCL10." (PMID 38506049, 2024).
acute myeloid leukemia (19 papers, 2013 to 2024). Acute myeloid leukemia (AML) is a group of neoplasms arising from precursor cells committed to the myeloid cell-line differentiation. "In acute myeloid leukemia (AML) the down-regulation of activating receptors NKp30/NCR3 and NKp46/NCR1 correlates with defective NK-cell cytotoxicity and poor leukemia prognosis." (PMID 24391641, 2013).
viral infection (13 papers, 2008 to 2023). "Researchers identified a unique CD8+ T-cell cluster expressing innate-like NCR3 protein in healthy donors and patients with viral infection." (PMID 36969251, 2023).
COVID-19 (11 papers, 2021 to 2023). A disease caused by infection with severe acute respiratory syndrome coronavirus 2. "The relationship between NCR3 and COVID-19/IS is currently unclear, although rs2857595 variants near NCR3 seem to be associated with increased risk of noncardioembolic stroke." (PMID 36969251, 2023). "Comparison between the disease conditions indicated significantly stronger expression of certain NK cell receptors (CD160, KLRC2, KLRC3, KLRF1, KIR3DL2, NCR1, NCR3) along the SLEC lineage in mild COVID-19 compared to severe COVID-19." (PMID 36591270, 2022). "Correlation analysis showed that NCR3 was positively associated with the change of CD8+ T cells and T helper 2 cell in both COVID-19 and IS patients (r > 0.3, P < 0.001) which indicating a close relationship between hub genes and the profile of immune cell variation." (PMID 36969251, 2023). "The results indicated six hub DEGs for comparison of T1DM and COVID-19 convalescence (CD3G, YES1, ALAS2, MYO1C, NCR3, PRKACB) and two hub DEGs for comparison of T2DM and COVID-19 convalescence (PTRF, EHD1)." (PMID 38169604, 2023). "We demonstrated the downregulation of IFITM10, CH25H, NCR3, and KLRK1 and the upregulation of ID1 in the PBMCs from RTP patients compared with that from patients with moderate or severe COVID-19." (PMID 34687295, 2021).
breast carcinoma (10 papers, 2013 to 2022). "Here we show that the surface expression of NCR1and NCR3 in NK cells from breast cancer patients, though lower than normal subjects, this difference was not statistically significant." (PMID 28145491, 2017). "We analysed the expression of the NCRs, NCR1, NCR2, and NCR3 in NK cells from breast cancer patients and healthy donors using flow cytometry." (PMID 28145491, 2017). "Moreover, the expression of NCR1 and other NK cell-associated genes, i.e., CD1d, DNAM-1, CRTAM, CD96, and NCR3/NKp30, was associated with prolonged disease-free survival (DFS) of breast cancer patients." (PMID 32038612, 2019). "Unsupervised clustering performed on the filtered gene set and based on DNAM1, NCR3(NKp30), CD96 and Class I–Restricted T-cell–Associated Molecule (CRTAM) expression signatures was able to spontaneously segregate the breast cancer patients in two distinct cohorts." (PMID 23758773, 2013).
lymphoma (8 papers, 2014 to 2025). A malignant (clonal) proliferation of B- lymphocytes or T- lymphocytes which involves the lymph nodes, bone marrow and/or extranodal sites. "However elevated level of NKp30/NCR3 specific RNA was detected in AIDS-RL in comparison with HIV patients without lymphoma, despite identical surface expression of NKp30/NCR3." (PMID 25908934, 2014).
malaria (8 papers, 2009 to 2023). Malaria is a serious and sometimes fatal disease caused by a parasite that commonly infects a certain type of mosquito which feeds on humans. "Here, we report the impact of the two NCR3 variants on susceptibility to pediatric malaria and SMA throughout a 36-mos." (PMID 37704951, 2023). "Variation in NCR3 alters susceptibility to malaria and SMA during the acquisition of naturally-acquired malarial immunity." (PMID 37704951, 2023). "A variant located in the promoter region of NCR3, rs2736191:C > G, has been associated with increased mild malaria episodes in carriers of the mutant allele (C allele, which corresponds to G allele in the current study) in Burkina Faso and Congo." (PMID 37704951, 2023). "Genome-wide linkage studies have mapped mild malaria resistance genes on chromosome 6p21, whereas NCR3-412 polymorphism (rs2736191) lying within this region was found to be associated with mild malaria." (PMID 30533319, 2018). "Nevertheless, we cannot exclude that there was an association of NCR3 with severe malaria with a small effect size." (PMID 30533319, 2018). "Here we considered NCR3 as a candidate gene for severe malaria, and analysed its polymorphism in P. falciparum-infected individuals." (PMID 30533319, 2018). "NCR3 that is also located within chromosome 6p21.3 has been shown to be associated with mild malaria in Burkina Faso and in the Republic of Congo." (PMID 30533319, 2018). "We investigated a NCR3 genetic variant, which was linked and associated with mild malaria in Burkina Faso." (PMID 30533319, 2018). "Noticeably, the 1-LOD drop area contained only five genes, and among them, TNF, LTA, and NCR3 have been associated with mild malaria or parasitaemia." (PMID 24884991, 2014). "Since NCR3 can activate NK cells to clear malaria parasites by directly recognizing pRBCs, decreased NCR3 expression in TT carriers could reduce antiparasitic effects and result in increased susceptibility to malaria." (PMID 37704951, 2023). "Population based studies conducted in sub-Saharan Africa have identified a single nucleotide polymorphism (SNP) in the promoter for the NCR3 gene that encodes NKp30 that is associated with an increased number of clinical, uncomplicated malaria episodes in individuals over 5 years old." (PMID 31921133, 2019). "In this way, our power analysis for genetic association indicated that we could detect an association of NCR3 with severe malaria when assuming an effect size similar to the one we calculated for mild malaria in Burkina Faso or in the Republic of Congo." (PMID 30533319, 2018). "Linkage studies have revealed a linkage of mild malaria to chromosome 6p21 that contains the NCR3 gene encoding a natural killer cell receptor, whereas NCR3-412G>C (rs2736191) located in its promoter region was found to be associated with malaria in Burkina Faso." (PMID 29121672, 2017). "In addition, several polymorphisms found under the linkage peak, and more precisely, within TNF, LTA and NCR3 genes, were independently associated with subphenotypes of mild malaria such as parasitaemia or mild malaria attack in Burkina Faso." (PMID 29121672, 2017). "Notably, a recent study reported an association with a promoter polymorphism in the NCR3 gene and mild malaria attacks and a haplotype that contained the polymorphism was significantly associated with increased risk of mild malaria." (PMID 19409086, 2009). "As such, we examined the impact of genetic variation in the gene encoding a primary NK cell receptor, natural cytotoxicity-triggering receptor 3 (NCR3), on the occurrence of malaria and SMA episodes over time." (PMID 37704951, 2023). "Susceptibility to malaria, SMA, and all-cause mortality was determined in carriers of NCR3 genetic variants (i.e., rs2736191:C > G and rs11575837:C > T) and their haplotypes." (PMID 37704951, 2023). "Variations in several host genes (HBB, IL4, IL12, TNF, LTA, NCR3 and FCGR2A) have been reported to be associated with malaria outcome." (PMID 24066864, 2013).
malaria (continued). "Besides, we did not detect an association of severe malaria with NCR3 genetic variation." (PMID 30533319, 2018). "Also, NCR3-412 polymorphism may partly explain why individuals with asymptomatic malaria have mild malaria attacks, but is unlikely to explain why some patients with mild malaria develop severe forms of the disease." (PMID 30533319, 2018). "In the later case, the NCR3 expression may not influence the occurrence of severe malaria." (PMID 30533319, 2018).
lung carcinoma (6 papers, 2019 to 2025). "Human NK cells express both NCR1 and NCR3 at high levels, and low expression of NCR3 specifically has been associated with poor prognosis in lung cancer." (PMID 40443661, 2025).
non-small cell lung carcinoma (6 papers, 2018 to 2025). A group of at least three distinct histological types of lung cancer, including non-small cell squamous cell carcinoma, adenocarcinoma, and large cell carcinoma. "Moreover, high NCR3 and NKp30a absolute expression levels are positive prognostic biomarkers in patients with non-small cell lung cancer." (PMID 38698855, 2024).
primary Sjögren’s syndrome (6 papers, 2016 to 2024). "Both rs2736191 and another NCR3 variant rs11575837:C>T (located in the non-coding region of exon 1) have been shown to be inversely associated with risk of primary Sjögren’s syndrome (pSS), and the minor T allele of rs11575837 is associated with reduced NCR3 gene transcription." (PMID 37704951, 2023). "Furthermore, the impact of the NCR3 protein has been observed in various other diseases, such as Sjögren’s syndrome and cancer-related disorders." (PMID 38714580, 2024).
AIDS (5 papers, 2014 to 2019). A syndrome resulting from the acquired deficiency of cellular immunity caused by the human immunodeficiency virus (HIV). "On the contrary, NKp30/NCR3 RNA was overexpressed in AIDS-RL patients (normalized ratio >2 for the 7 patients analyzed)." (PMID 25908934, 2014).
endometriosis (4 papers, 2018 to 2022). The growth of functional endometrial tissue in anatomic sites outside the uterine body. "NKp30 (NCR3) and its ligand BAT3 (BAG6) were significantly upregulated in 6/6 and 4/6 secretory phase datasets from endometriosis patients respectively compared with control patients (1.2–1.7 fold change and 1.4–2.3 fold change respectively)." (PMID 30021652, 2018).
autoimmune disease (3 papers, 2017 to 2025). A disorder resulting from loss of function or tissue destruction of an organ or multiple organs, arising from humoral or cellular immune responses of the individual to their own tissue constituents. "According to the literature data, the rs1052248 polymorphism of the NCR3 gene has been very poorly investigated to date and there are no publications enabling us to compare the results of our present study with other cohorts of patients suffering from RA, AS, or other autoimmune diseases." (PMID 38714580, 2024).
diabetes mellitus (2 papers, 2020 to 2021). A metabolic disorder characterized by abnormally high blood sugar levels due to diminished production of insulin or insulin resistance/desensitization. "Phenotypes in the Metabolic cluster share two significant genes, and NCR3 has been previously associated with both diabetes mellitus and IgG glycolysation." (PMID 32245788, 2020). "The immune-related genes (NCR3 and TNF) and immune cells (NK cells) may play a vital regulatory role in the occurrence and development of T1DM, which possibly provide new ideas and potential targets for the immunotherapy of diabetes mellitus (DM)." (PMID 34311758, 2021).
acute GVHD (1 paper, 2024). "We found weak genetic associations between polymorphisms in the CD226, CD244, FCGR3A, KLRD1, NCR3, and PVRIG genes, and the risks for relapse, acute GVHD, and chronic GVHD in the HSCT discovery cohort but not in the replication cohort." (PMID 39506082, 2024).
acute leukemia (1 paper, 2013). A clonal (malignant) hematopoietic disorder with an acute onset, affecting the bone marrow and the peripheral blood. "High circulating TGF-β level correlates with poor prognosis in acute leukemia and is linked to reduced NK-cell activity with reduced expression of NKp30/NCR3 and NKG2D." (PMID 24391641, 2013).
Arthritis (1 paper, 2024). Inflammation of a joint. "These genes are situated within the MHC class III region, specifically in the Ltab-Ncr3 conserved haplotype, which has a significant association with arthritis pathogenesis and progression." (PMID 38714580, 2024).
colitis (1 paper, 2025). Inflammation of the colon. "Nonetheless, a UC-specific pathway called the BAG6-NCR3 axis led to higher levels of inflammatory cytokines and increased the cytotoxicity of NCR3+ NK cells, thereby contributing to the persistence of colitis." (PMID 39752457, 2025).
interstitial lung disease (1 paper, 2019). A diverse group of lung diseases that affect the lung parenchyma. "Similarly, during anti-synthetase syndrome, an autoimmune connective tissue disease associated with interstitial lung disease, the NKp30 (NCR-3)/BAT-3 axis could promote the disease." (PMID 31275301, 2019).
steatosis (1 paper, 2023). Increased lipid within the cytoplasm of cells. "The heterogeneity of peripheral NK cells has also been shown in the development of NASH from simple steatosis with a decreased expression of NK cell activation marker natural cytotoxicity receptor 3 (NCR3, also known as NKp30) in NASH." (PMID 37239062, 2023).
type 1 diabetes (1 paper, 2020). "Of the remaining five genes, three [MICA, NCR3, and TAP2] have been previously associated with type 1 diabetes, while APOM and HLA-DRB5 have been associated with RA." (PMID 32245788, 2020).